IL17A (interleukin 17A)
Diseases named in the same sentence as IL17A in open-access papers (continued):
Sharing a sentence is not in itself a finding about the gene and the disease.
fungal infections (continued). "Additionally, with fungal infection, there were significant differences between the patient groups and control group (p = 0.002, 0.01) in the genotypes (GG, GA, and AA) of IL-17A and the genotypes (CC, CG, and GG) of IL-6 G-174C.correspondingly." (PMID 39289412, 2024). "Similarly, IL-17A functions as a key proinflammatory cytokine essential for defensing against bacterial and fungal infections, while IL-22 plays diverse roles in inflammation, mucous production, pathogen defense, wound healing, and tissue regeneration." (PMID 39328419, 2024). "Notably however, in a mouse model of local fungal infection using CD4+ T cell-deficient mice, IL-17A-secreting CD8+ T cells were able to compensate for the lack of Th17 cells and provided protection against oropharyngeal candidiasis." (PMID 38567057, 2023). "Furthermore, mucocutaneous candidiasis is a known complication of anti-IL-17A antibody therapy, highlighting the importance of IL-17 for defense against fungal infections." (PMID 38567057, 2023). "A recent investigation on the effect of KoRV on cytokine expression shows a reduced presence of IL17A, suggesting an increased susceptibility of hosts to Gram-negative bacterial and fungal infections." (PMID 35457470, 2022). "Ixekizumab (anti‐IL‐17A) improved patient's ichthyosis, however, worsened fungal infection." (PMID 35665208, 2022). "Zebrafish have homologs for both il22 and il17a, and il22 mRNA expression is induced upon fungal infection in adult zebrafish, but their roles in fungal infections in larval zebrafish are unknown." (PMID 35333905, 2022). "As IL-17A plays a pivotal role in host protection against fungal infections, patients treated with secukinumab may develop oral candidiasis." (PMID 34103043, 2021). "Although IL-17A and IL-17F are highly homologous, they perform distinct functions: IL-17A plays important roles in inflammation, autoimmunity, and host defenses against bacterial and fungal infections; whereas IL-17F is mainly involved in mucosal host defense mechanisms." (PMID 34733288, 2021). "IL-17A is a member of the IL-17 family, which consists of IL-17A through IL-17F, that participates in tissue inflammation, where it aids especially against cutaneous bacterial and fungal infections." (PMID 33670423, 2021). "One clinical study has reported that higher incidence of fungal infections accompanied with severe intestinal pathology were observed in patients with Crohn's disease upon IL-17A blockade, indicating the possible role of IL-17 pathway in regulating fungal communities in the gut." (PMID 32322167, 2020). "Since IL-17A has an important role in protecting against fungal infections and given that PMNs are capable of producing IL-17 during infections, we investigated whether this cytokine is produced following gp43 stimulation." (PMID 31886295, 2019). "Within this combined clinical and experimental investigation, an NGS-based diagnostic approach and plasmatic measurements of MR-proADM and/or IL-17A were identified to be suitable for a comprehensive, reliable, and fast diagnosis of mycoses in patients suffering from septic shock." (PMID 28820494, 2017). "Moreover, MR-proADM and IL-17A in plasma proved suitable for the identification of patients with a fungal infection." (PMID 28820494, 2017). "IL-17A is the signature cytokine in various diseases, particularly the development of autoimmunity, inflammation, and tumors, and also plays important roles in host defense against bacterial and fungal infections." (PMID 27389701, 2016). "IL-17A contributes to protection against bacterial and fungal infections." (PMID 25140115, 2014). "However, as IL-17A is essential in protection against fungal infections, patients treated with this drug may develop candidiasis." (PMID 34103043, 2021). "Thus, it is possible that TLR4 binding to gp43 drives both PGE2 production and inhibition of IL-17A production by PMNs, a mechanism that could lead to poor control of the fungal infection." (PMID 31886295, 2019).
fungal infections (continued). "Thus, our data suggest that gp43 from P. brasiliensis might modulate host susceptibility to the fungal infection by affecting PGE2 and IL-17A production." (PMID 31886295, 2019). "To further confirm this, we measured the protein level of IFN-γ, IL-17A, and TNF-α under fungi infection in both healthy donors and IBD patients." (PMID 37124046, 2023). "Interleukin 17A (IL-17A), which is secreted by CD8+ T cells, mediates the immune response and protects the host from fatal fungal infections." (PMID 37251371, 2023). "Because Il17a transcript levels were elevated in the HNI + OPC condition, we next determined if IL-17/IL-17RA were still protective against fungal infection during this specific form of immunosuppression." (PMID 35628751, 2022). "Further, a significant variation in IL-17A, TNF-β, IL-1β, IL-2, IL-4, IL-6, IL-8, IL-10, IL-22, and IL-12p70, between the uninfected group and the pulmonary bacterial and fungal infection group (P < 0.05) was observed." (PMID 36319826, 2022). "In fungal infections, a mixed TH1/TH17 immune response confers resistance through the secretion of cytokines such as IFN-γ, TNF-α and IL-17A, which activate neutrophils and macrophages for fungal killing and clearance." (PMID 29520092, 2018). "Type 17 inflammation is more characteristic of fungal infection, and typified by neutrophilia and CD4+ Th17 cells with the ability to make a distinctive range of cytokines, including IL-17A (which we will refer to as IL-17)." (PMID 27256370, 2016). "A loss in the homeostasis of STAT3-mediated Th17 polarization and a lack of IL-17A and Th17 secreted cytokines parallel the Th1 overactivation and lead to an imbalanced defense against fungal infections." (PMID 36826612, 2023). "Antibodies specific for IFN-α7 and IL-22 were significantly more prevalent in patients with only bacterial infections and patients with mixed bacterial/fungal infections, and antibodies against IFN-α10, IL-17A, and TNF-α were more common in patients with mixed bacterial/fungal infections." (PMID 36752204, 2023). "In mice, activated MAIT cells primarily produce IL-17A, a cytokine important for control of some fungal infections, but not Pneumocystis, as IL-17A knockout mice can control the infection similarly to C57BL/6 mice." (PMID 35736127, 2022). "IL-17A is produced by a subset of CD4+ T cells, Th17 cells, which are part of the adaptive immune system and take a critical part in defense against extracellular bacterial and fungal infections." (PMID 34072201, 2021). "Patients failed to increase IL-17A, IL-22, and IL-23, which are found critical for optimal host defense against cutaneous candidiasis and fungal infections." (PMID 28919897, 2017). "From our studies, it can be inferred that initial production of IL-1β may induce IL-17A and CAMP production which can in turn positively regulate further production of IL-1β to create an inflammatory environment which limits fungal infection." (PMID 22174673, 2011). "The detection of IL-17a-producing CD8+ T cells in Apt-TA-2m immunized mice may reflect a Tc17-like response that contributes to mucosal or tissue-specific immunity, as reported in models of viral and fungal infections." (PMID 40539075, 2025). "Th17 cells can directly activate the local immune response by secreting cytokines, such as IL-17A and IL-17F, which promote the production of various inflammatory mediators (such as IL-6 and TNF-α), thus increasing the intensity of the inflammatory response against bacterial or fungal infections." (PMID 39794999, 2024).
diabetes (255 papers, 2011 to 2026). "Antibody-mediated inhibition of CD137L markedly reduced diabetes-driven bone loss, neutrophil recruitment, expansion of γδ T cells, and excessive infiltration by IL-17A+ cells." (PMID 41379565, 2025). "A clinical study based on blood samples collected from 56 patients with nephropathy and 57 patients with diabetes revealed that patients carrying at least one allele of the IL-17A (rs2275913) gene polymorphism were vulnerable to DKDs." (PMID 36776877, 2023). "Previous clinical and animal studies have further demonstrated that increased oral microbial pathogenicity in diabetes is linked to increased inflammation and IL-17A expression." (PMID 35859767, 2022). "Of note, a previous study performed in patients with type 2 diabetes mellitus reported an inverse association between irisin and interleukin (IL)-17A, one of the main pro-inflammatory cytokines implicated in the pathogenesis of axSpA." (PMID 35898516, 2022). "Although the cause of diabetic retinopathy is multifactorial, IL-17A is a prevalent inflammatory cytokine involved in the promotion of diabetes-mediated retinal inflammation and the progression of diabetic retinopathy." (PMID 33919327, 2021). "In IL-17A knockout mice with STZ induced diabetes, renal lesions were more severe in IL-17A deficient mice than in wild-type mice." (PMID 31963845, 2020). "We measured traditional CVD risk factors [blood pressure, Body Mass Index (BMI), diabetes, age, sex, smoking], serum markers of systemic inflammation (hsCRP, GlycA) and metabolic dysfunction (cholesterol efflux capacity), and inflammatory cytokines (IL-1β, IL-6, IL-12/IL-23, IL-17A, TNF-α, IFN-γ)." (PMID 35720288, 2022). "Moreover, IL-17A deficiency ameliorates streptozotocin-induced diabetes." (PMID 26843788, 2015). "Several studies support that IL-17A mediates the pathogenetic mechanisms of Ang II in diabetes, hypertension, and cardiovascular disease models." (PMID 40260277, 2025). "The pro-apoptotic effects of IL17A on retinal endothelial cells were also highlighted in a study using a streptozotocin (STZ)-induced murine model of type 2 diabetes mellitus." (PMID 40136531, 2025). "TNF-α, IL-1β, IL-6, NF-κB and IL-17A are multifunctional cytokines, that are mainly related to immune regulation, and play a crucial role in the occurrence and progression of diabetes." (PMID 40046742, 2025). "Previous commercial ELISA kits for serum IL‐17A detection had detection thresholds that were too high to reliably measure IL‐17A levels in diabetes or DKD patients." (PMID 39946217, 2025). "Future studies with larger sample sizes and mechanistic investigations are warranted to validate these findings and explore the therapeutic implications of IL‐17A in diabetes‐related complications." (PMID 39946217, 2025). "In a mouse model of diabetes, mycophenolate mofetil attenuated diabetic nephropathy by reducing T lymphocyte infiltration in the kidneys, with an increase in IL‐17A+ CD4+ T cells observed as diabetic nephropathy progressed." (PMID 39946217, 2025). "Further, all anti-IL-17A-treated and -untreated diabetic mice had a 6h fasted blood glucose concentration greater than 275 mg/dL; 2- and 6-months post-diabetes." (PMID 36674854, 2023). "Researchers have also discovered that IL-17A is a characteristic proinflammatory cytokine in the serum and urine of patients with diabetes, and CD40 expression was observed to be increased in podocytes with DN." (PMID 36776877, 2023). "In the current study, we determined that diabetes-mediated IL-17A enhances vascular endothelial growth factor (VEGF) production in the retina, Muller glia, and retinal endothelial cells." (PMID 36675261, 2023). "Our previous studies provided evidence that diabetes induced immune cells to produce IL-17A that migrated through the retinal vasculature, induced retinal inflammation, and vasculature impairment." (PMID 36674854, 2023).
diabetes (continued). "On the immune-mediated kidney disease, Th17 cells are likely to get upregulated in DKD, resulting in a general increase of IFN-γ and IL-17A in streptozotocin (STZ)-induced diabetes." (PMID 36776877, 2023). "A previous study reported mtDNA changes in blood and urine potentially related to a specific inflammatory response, including IL-17A serum levels in kidney disease in type 2 diabetes mellitus patients." (PMID 37895262, 2023). "In conclusion, diabetes-mediated VEGF production was significantly decreased when IL-17A was ablated or neutralized in murine models of Type I and II diabetes." (PMID 36675261, 2023). "Through in vivo neutralization of IL-17A in murine models of Type I and II diabetes, we did determine that diabetes-mediated IL-17A does enhance VEGF." (PMID 36675261, 2023). "Overall, these data provide evidence that diabetes-mediated IL-17A enhances VEGF production in the retina." (PMID 36675261, 2023). "Levels of IL-17A in retinal protein lysates (n = 3 samples of 3 pooled retinas/group) were analyzed by ELISA 6 months post-diabetes." (PMID 36674854, 2023). "Although anti-IL-17A antibody has not been evaluated for DKD treatment, recent research demonstrated that IL-17A was involved in diabetes-mediated renal damage." (PMID 36646672, 2023). "Th17-polarized cells from non-obese diabetic mice following mycobacterial adjuvant immunotherapy delay the development of type 1 diabetes, indicating the protective effects of IL-17A against diabetes." (PMID 36902720, 2023). "Previously, we determined that diabetes-mediated IL-17A enhanced retinal inflammation, vascular leakage, and capillary degeneration." (PMID 36675261, 2023). "IL-17A and Th17 cells have been confirmed to participate in various types of diabetes and accumulate multiple organ complications." (PMID 35392087, 2022). "It has been reported that IL-17A−/− reduces diabetes-mediated retinal inflammation, oxidative stress, and vascular leakage in streptozotocin-induced diabetic mice." (PMID 34750361, 2021). "In this regard, the specific effects of IL-17A in autophagic response on the pathogenesis of diabetes have yet to be elucidated." (PMID 33691614, 2021). "On the other hand, it has been proved that the increased cytokine production by Th1 (IFN-γ, IL-2, TNF-α, and TNF-β) and Th17 (IL-6, IL-17A, and IL-17F) in diabetics can affect the HbA1c level." (PMID 33746897, 2021). "Recently, when diabetes-mediated IL-17A production was ablated by therapeutically inhibiting RORγt, retinal capillary degeneration was ameliorated and the onset of non-proliferative diabetic retinopathy was halted." (PMID 33919327, 2021). "Previously, we determined that diabetes induced IL-17A production, which enhanced retinal inflammation, oxidative stress, and retinal capillary degeneration in streptozotocin (STZ)-induced diabetic mice." (PMID 33919327, 2021). "Taken together, these results suggest the VAF347 treatment regimen is sufficient to halt diabetes-mediated IL-17A and Th17 cell differentiation." (PMID 33919327, 2021). "Previous studies provide evidence that diabetes mediates Muller glia to produce IL-17A, which plays a role in the onset and progression of diabetic retinopathy." (PMID 33919327, 2021). "In contrast, contradictory data have been described in experimental DN regarding the protective impact of IL-17A on the incidence of diabetes." (PMID 31963845, 2020). "In diabetes, IL-17A-producing cells migrate through and adhere to the retinal vasculature, wherein IL-17A crosses the blood-retina-barrier and binds to its receptor, which is expressed on photoreceptors, Muller glia, and retinal endothelial cells." (PMID 32429598, 2020). "Accordingly, in IL-17A knockout mice with STZ induced diabetes, hyperglycemia and insulitis were milder than in wild-type mice." (PMID 31963845, 2020). "IL-17A has been identified as an important cytokine in the promotion of diabetes and the progression of diabetic complications." (PMID 32429598, 2020).
diabetes (continued). "Taken together these previous studies provide evidence that diabetes-mediated IL-17A is pivotal in the onset of diabetic retinopathy." (PMID 32429598, 2020). "In our current study, we discovered that SR1001 treatment ablated diabetes-mediated IL-17A production, which in turn significantly decreased leukostasis in the retinal vasculature, retinal inflammation, and VEGF production." (PMID 32429598, 2020). "Several preclinical studies have confirmed the contribution of Th17 cells and IL-17A to diabetes and diabetes end-organ damage, pointing to Th17/IL17A blockade as beneficial in diabetes." (PMID 31963845, 2020). "Diabetes induces Interleukin (IL)-17A production, which is one of the most prevalent cytokines associated with inflammatory pathogenesis." (PMID 32429598, 2020). "In our results, positive correlations of Firmicutes with pro-inflammatory IL-1β, TNF-α, IL-6, IL-17A and LPS demonstrated that both pro-inflammatory indicators and Firmicutes contributed to pathogenesis of diabetes." (PMID 32028957, 2020). "Some preclinical studies have demonstrated the beneficial effects of Th17/IL-17A blockade in diabetes." (PMID 31963845, 2020). "Mice that lost weight due to IL-17A deliveryshowed regular fasting glucose levels, thereby excluding overt diabetes in thesemice." (PMID 26964500, 2016). "It has been shown that in vitro treatment of OT1 cells with IL-23 promotes their differentiation into IL-17 producing CD8+ T cells (Tc17) and causes diabetes in an IL-17A- and IL-17F-dependent manner when adoptively transferred to RIP-OVA mice." (PMID 22229105, 2012). "In this study, we have identified a group of APMB-specific analytes (IL-10, CXCL1, IL-12p40, IL-13, CCL22, CCL4, IL-17A, and TGFα) that correlates with several clinical phenotypes associated with more severe SAB (diabetes, dialysis dependence, metastatic infection, and cardiac vegetation)." (PMID 39966757, 2025). "Furthermore, IL-21 overexpression in pancreatic β-cells led to increased expression of inflammatory mediators such as IL-17A, IL-17F, IFN-γ, MCP-1, MCP-2, and IP-10, whereas IL-21R deficiency conferred protection against insulitis and diabetes in NOD mice." (PMID 40979706, 2025). "However, measuring serum IL‐17A levels in diabetes patients presents significant challenges, as its concentrations are typically very low—often just a few pg/mL—and are difficult to detect with conventional methods." (PMID 39946217, 2025). "Besides, diabetes induces cells to secrete IL17A, which in turn leads to a variety of complications." (PMID 38250601, 2024). "Similarly, weekly intraperitoneal injections of 50 μg/mL of anti-IL-17A significantly decreased (p < 0.05) diabetes-mediated IL-1β, IL-6, TNF-α, and ZO-1 degradation in the retinas of db/db-Type II diabetic mice 2 months post-diabetes." (PMID 36674854, 2023). "Finally, we designed an anti-IL-17A treatment regimen in a murine model of Type II diabetes that halted diabetes-mediated retinal inflammation, vascular impairment, and the onset of diabetic retinopathy." (PMID 36674854, 2023). "Finally, retinal capillary degeneration was halted 6 months after diabetes was confirmed in Type II-diabetic mice that received weekly intraperitoneal injections of anti-IL-17A." (PMID 36674854, 2023). "Presence of IL-17A in individuals with diabetes and diabetic mouse models is an obvious characteristic, and serum and urinary levels of IL-17A in the former with advanced DKD confirms this finding; additionally, low doses of IL-17A have a noteworthy therapeutic effect on podocytes and tubular cells." (PMID 36776877, 2023). "Additionally, an anti-IL-17A intravitreal injection was capable of halting diabetes-mediated ZO-1 degradation 6 weeks after injection." (PMID 36674854, 2023). "IL-17A knockout reduces the levels of TNF-a, IFN-c and IL-1b in Akita mice, suggesting that IL-17A is strongly associated with proinflammatory cytokine-driven inflammatory responses in diabetes progression." (PMID 36582230, 2022).